DEFT1P2 (defensin theta 1, pseudogene 2)
Gene: Transcribed unprocessed pseudogene on chromosome 8 (7,006,471 to 7,007,389, reverse strand). Ensembl gene ENSG00000232039.
Diseases named in the same sentence as DEFT1P2 in open-access papers:
DEFT1P2 is named in the same sentence as 1 disease in open-access papers, as found by Europe PMC text mining. Sharing a sentence is not in itself a finding about the gene and the disease. The quoted sentences say what the papers report.
Cryptococcal meningitis (1 paper, 2019). Meningeal inflammation produced by cryptococcus neoformans, an encapsulated yeast that tends to infect individuals with acquired immunodeficiency syndrome and other immunocompromised states. "The expression of the lncRNAs, ECRP, LINC00968, DPY19L1p1, DEFA8P, and DEFT1P2 was higher but the expression of the lncRNAs DDX11L10 and MTMR9LP was lower in cryptococcal meningitis patients than in healthy controls, which was consistent with the chip analysis results." (PMID 30767376, 2019).